FIS1 (fission, mitochondrial 1)
Diseases named in the same sentence as FIS1 in open-access papers (continued):
Sharing a sentence is not in itself a finding about the gene and the disease.
Obesity (13 papers, 2017 to 2025). Accumulation of substantial excess body fat. "Furthermore, in skeletal muscle of mice with genetic obesity and with diet-induced obesity, it was also observed mitochondrial fragmentation and increased mitochondrion-associated Drp1 and Fis1." (PMID 32215168, 2020). "In mice fed an HFD for 12 weeks to induce more profound obesity and metabolic dysregulation, Ad-Fis1 significantly increased both glucose and insulin tolerance compared with control mice." (PMID 35015731, 2022). "On the other hand, Drp1 and Fis1 were increased in liver from db/db mouse as well as in mice with high-fat diet-induced obesity, resulting in impaired mitochondrial function." (PMID 32215168, 2020). "Conversely, Western blot results demonstrated increased levels of mito-fission related Fis1 in adipose tissue of control HFD-fed mice an effect of obesity that was completely prevented in adipose tissue of the Lnv-adipo-HO-1 mice fed an HFD." (PMID 31906399, 2020). "Interestingly, although knocking down Mfn1 in the liver confers protection to mice against high-fat diet-stimulated insulin resistance and obesity, inhibiting the division-related proteins Fis1 and Drp1 in cells impairs cell respiration and insulin secretion." (PMID 40851002, 2025). "This study also showed that, in the HFD-Con group, where obesity was induced, the expression of proteins related to mitochondrial fission, Drp1 and Fis1, increased, whereas the expression of proteins related to mitochondrial fusion, Mfn1, Mfn2, and Opa1, decreased." (PMID 31010272, 2019). "This increase in fusion (MFN1 and MFN2) and decrease in fission (FIS1) contribute to an increase in overall mitochondrial function, leading to a decrease in adiposity in HF fed mice, a consequent reduction in obesity, and a concurrent reduction in the development of NASH." (PMID 30057822, 2018). "Results obtained in this work are supported by previous observations showing that the SKM of individuals with obesity and T2DM displays lower expression of Fis1 and DRP1 and higher Mfn1/2 expression relative to healthy subjects." (PMID 37627494, 2023). "While another study found Mfn1 and Mfn2 but not Opa1 were decreased, and Drp1 and Fis1 were increased in skeletal muscle of HFD-induced obesity mice." (PMID 29245950, 2017).
Alzheimer disease (9 papers, 2017 to 2025). A progressive, neurodegenerative disease characterized by loss of function and death of nerve cells in several areas of the brain leading to loss of cognitive function such as memory and language. "In the AppNL-F knockin mouse model of Alzheimer’s disease, increased turnover resulted from imbalances in both synthesis and degradation, converging on proteins associated with synaptic vesicle recycling (Dnm1, Cltc, Rims1) and mitochondria (Fis1, Ndufv1)." (PMID 34979241, 2022). "For instance, in neurons from the hippocampus of Alzheimer’s disease patients, reduced expression of Opa1, Mfn1/2, and Drp1, along with increased Fis1 levels, has been observed." (PMID 41465333, 2025). "Among candidate modifier genes involved in neurological development and functioning, at least four genes are closely related to Alzheimer’s disease including FIS1, DDX39B, PRND, GSTM3." (PMID 36553485, 2022). "In the pathological study of Alzheimer's disease and Huntington's disease, fis1 was found to aggravate the aggregation of DRP1 in mitochondria by interacting with DRP1 oligomers, which can induce mitochondrial division." (PMID 32587661, 2020). "Pretreatment with SS-31 also reversed alterations in the expression of the mitochondrial proteins dynamin-related protein (DRP) 1, FIS1, mitofusin (MFN) 1, MFN2, and OPA1 in Alzheimer disease." (PMID 34221235, 2021).
hepatocellular carcinoma (8 papers, 2018 to 2024). A malignant tumor that arises from hepatocytes. "Another example of this association is in hepatocellular carcinoma; here Ca2+ increase promotes MT fission by up-regulating expression of Drp1 and Fis1." (PMID 29438347, 2018). "Overexpression of Fis1 and Drp1 not only promotes mitochondrial hyperfission but also promotes cell metastasis of hepatocellular carcinoma cells." (PMID 39571196, 2024). "Strengthening the importance of investigating novel PTMs, recent research identifying a new and critical PTM on FIS1 by MET demonstrates the necessity of this signaling pathway to drive metastatic dissemination in hepatocellular carcinoma." (PMID 35356277, 2022). "Recently an elegant study was published, where RTK MET was described in a novel signaling pathway with FIS1/DRP1 that promotes mitochondrial fragmentation and metastasis in hepatocellular carcinoma cells." (PMID 35356277, 2022). "To determine whether ASOs can be used to modulate mitochondrial dynamics, we administered a panel of ASOs targeting mitochondrial fusion and fission factors (Mfn1, Mfn2, Drp1, Fis1, Mff, Mief1, Mief2) to MHT (mouse hepatocellular carcinoma) cells in culture." (PMID 34698563, 2022). "FIS1 Y38 phosphorylation by Met tyrosine kinase, a receptor for hepatocyte growth factor (HGF), promotes mitochondrial fission and facilitates hepatocellular carcinoma (HCC) tumor growth." (PMID 37627290, 2023).
lung carcinoma (8 papers, 2018 to 2024). "High expression of FIS1 has been reported in patient samples of oral melanoma, and the mitochondrial fission induced by FIS1 in lung cancer stem cells leads to autophagy and cancer cell survival." (PMID 37627290, 2023). "An elevation in FIS1, when observed together with other prognostic markers for lung cancer progression, was found to correlate with shorter overall survival." (PMID 34051059, 2021). "We found that there is an inverse relationship between FIS1 expression and the clinical stage of lung cancer." (PMID 34051059, 2021). "Third, we determined the clinical relevance of FIS1 in lung adenocarcinoma by analyzing the relationship between the expression of FIS1 in lung cancer patients and the clinical stage of lung cancer in the TCGA database." (PMID 34051059, 2021). "The mitochondrial kinetic regulator FIS1 mediates mitophagy in AML and lung cancer cells and depletion of FIS1 can cause attenuation of mitochondrial autophagy and lead to GSK3 inactivation, myeloid differentiation, cell cycle arrest, and severe loss of LSC self-renewal potential." (PMID 37422448, 2023). "In blood serum, in the group of lung cancer patients, the level of MFN1 protein was significantly higher (p < 0.01; Mann–Whitney U test) and the FIS1 protein level was significantly lower compared to the healthy control group (p < 0.001; Mann–Whitney U test)." (PMID 39199596, 2024).
Huntington disease (7 papers, 2018 to 2023). Huntington disease (HD) is a rare neurodegenerative disorder of the central nervous system characterized by unwanted choreatic movements, behavioral and psychiatric disturbances and dementia. "While Drp1/Fis1 PPI is critical for mitochondrial fission and homeostasis, excessive Drp1/Fis1 interaction, on the other hand, has been linked to some pathological conditions, including Parkinson’s and Huntington’s diseases." (PMID 36982862, 2023). "Evidence also showed that cardiac dysfunction in Huntington’s disease is related to DRP1/FIS1-mediated impairment of lysosomal function." (PMID 32292354, 2020). "Also, treatment with P110, which inhibits the DRP1/FIS1 interaction, improves mitochondrial homeostasis in cardiomyocytes and promotes the removal of damaged mitochondria in Huntington’s disease models." (PMID 32292354, 2020). "Strikingly, while inhibiting the interaction between Drp1 and Fis1 slowed the progression of neurodegenerative disorders, treatment with the Drp1/Mff-specific inhibitor accelerated disease progression in a mouse model of Huntington’s Disease." (PMID 30232469, 2018). "Drp1 has been found to interact with fission 1 (Fis1), leading to excessive mitochondrial fragmentation and production of reactive oxygen species (ROS) along with lysosomal dysfunction when PolyQ77 was expressed in cardiac models of Huntington’s disease (H9C2 cells)." (PMID 35054963, 2022). "In addition, tissues from Alzheimer’s disease (AD) and Huntington's disease (HD) patients demonstrated increased expression of DRP1 and FIS1, and decreased expression of MFN1, MFN2 and OPA1, indicating that an impairment on mitochondrial dynamics are associated with AD and HD." (PMID 33782711, 2021).
neuroblastoma (7 papers, 2018 to 2023). Neuroblastoma (NB) is the most common solid, extracranial childhood tumor. "We next examined the consequence of inhibiting Drp1/Fis1 interaction in another model of AD disease, neuroblastoma cells expressing a mutant form of APP, a mutation that is associated with FAS, found in a Swedish family (KM670/671NL)." (PMID 29464060, 2018). "Other studies have shown that expression of APP695 in M17 neuroblastoma cell line showed an increase in the level of mitochondrial fission 1 protein (FIS1), a fission protein, and decreased levels of mitofusin 1 (MFN1) and OPA1, proteins involved in fusion." (PMID 31824296, 2019). "In neuroblastoma cells treated with H2O2, calpastatin is able to alleviate disturbances in mitochondrial dynamics by decreasing mitochondrial fission protein (Fis-1 and Drp-1) levels." (PMID 34365571, 2022). "Dexamethasone increases ROS production and decreases the levels of mitochondrial fission proteins (Fis1 and DRP1) in human neuroblastoma cells." (PMID 32782788, 2020).
breast carcinoma (6 papers, 2013 to 2025). "Among these genes, NRIP1, HECA and FIS1 were of particular interest because they have previously been reported to be associated with breast cancer pathogenesis, and further studies of these genes will be pursued." (PMID 24355041, 2013). "Among these genes, NRIP1, HECA and FIS1 were of particular interest since they have previously been reported to be associated with breast cancer pathogenesis." (PMID 24355041, 2013). "As to solid tumors and leukemia, FIS1 was only involved in cell signaling pathways of breast cancer and prostate cancer, except for our antecedent studies." (PMID 24416201, 2014). "Met interaction with Fis1 could also occur in other types of human cancer cells like HCC1806 breast cancer cells and HT29 colon cancer cells, which was analogously enhanced by HGF but diminished by crizotinib." (PMID 34848680, 2021). "Finally, western blotting was employed to detect the expression of apoptosis‐related protein caspase‐3, cleaved‐caspase‐3, Bcl‐2, Bak, DRP1, and FIS1 to explore the effect of FLT on apoptosis in human breast cancer cells MCF‐7 and MBA‐MB‐231 along with the mechanism." (PMID 40761496, 2025). "However, adaptor proteins for Drp-1 on the outer mitochondrial membrane like MID49/MIEF2 or FIS1, were found to be decreased in the basal-like subtype when compared to the other breast cancer subtypes, and no changes among the different subtypes were observed in MFF, another Drp-1 adaptor protein." (PMID 31231612, 2019).
leukemia (6 papers, 2014 to 2026). A malignant (clonal) hematologic disorder, involving hematopoietic stem cells and characterized by the presence of primitive or atypical myeloid or lymphoid cells in the bone marrow and the blood. "The LSCs’ lower mitochondrial could be mediated by mitochondrial fission 1 protein (FIS1) clearance of dysfunctional mitochondria since mitochondrial fission mediated by FIS1 is necessary for LSC survival and Leukemia-initiating capacity." (PMID 37685874, 2023). "Furthermore, mitochondrial fission mediated by the mitochondrial fission 1 protein (FIS1) and downstream autophagy is necessary for AML LSCs survival and leukaemia-initiating capacity." (PMID 34561557, 2022).
acute kidney injury (5 papers, 2022 to 2025). Sudden and sustained deterioration of the kidney function characterized by decreased glomerular filtration rate, increased serum creatinine or oliguria. "FIS1 overexpression can lead to mitochondrial fragmentation during acute kidney injury." (PMID 36499050, 2022).
acute myeloid leukemia (5 papers, 2014 to 2021). Acute myeloid leukemia (AML) is a group of neoplasms arising from precursor cells committed to the myeloid cell-line differentiation. "FIS1 is a novel gene target associated with poor prognosis in pre-treatment patients with acute myeloid leukemia." (PMID 30404157, 2018). "FIS1 up-regulation decreased cellular ATP levels in anoxic cardiomyocytes and impaired glucose-stimulated insulin secretion in INS-1E cells; and it has been identified as a molecular marker for poor prognosis in patients with acute myeloid leukemia." (PMID 33330472, 2020).
sarcopenia (5 papers, 2017 to 2025). Progressive decline in muscle mass due to aging which results in decreased functional capacity of muscles. "Key proteins involved in mitochondrial fission, such as dynamin-related protein 1 (DRP1) and fission protein 1 (FIS1), are decreased in sarcopenia, impairing the isolation and removal of damaged mitochondria." (PMID 41568334, 2025). "Expression levels of Mfn2, Fis1, Drp1, and Opa1 in sarcopenic muscle are down-regulated, suggesting a role for mitochondrial dysfunction in the pathogenesis of sarcopenia and skeletal muscle atrophy." (PMID 36561214, 2022). "In another study, the expression levels of Mfn2, Fis1 and Opa1 were downregulated in sarcopenic muscle, suggesting that mitochondrial dynamics participates in the pathogenesis of sarcopenia." (PMID 34881083, 2021). "Hence, reductions of mitochondrial fission proteins (such as DRP1, MFF, and FIS1) in patients with sarcopenia inhibit mitophagy and leads to the accumulation of dysfunctional organs and muscle atrophy." (PMID 36561214, 2022). "Expression levels of FIS1 also decrease in old age, and older animals have lower levels of FIS1 and autophagy than younger animals, resulting in impaired autophagy in older muscles, while knockdown of FIS1 activates muscle atrophy in sarcopenia." (PMID 36561214, 2022). "Intriguingly, fusion-related proteins (Mfn1/Mfn2) were significantly upregulated in older wild type (WT) mice due to the downregulation of fission protein Fis1, which is consistent with the results obtained in some hip-fractured patients of advanced age with sarcopenia." (PMID 34881083, 2021).
type 2 diabetes (5 papers, 2019 to 2025). "We also observed that people with type 2 diabetes are characterised by low protein levels of FIS1, in comparison with endurance-trained athletes." (PMID 33258025, 2021). "Type II diabetes increases the protein level of liver rhythm molecule CLOCK and impairs the mitochondrial morphology, dynamics (OPA1 and Fis1), and mitophagy, which can be optimized by two differently timed exercises." (PMID 36012573, 2022).
colon carcinoma (4 papers, 2013 to 2022). "A conditional knockout model of FIS1 in colon carcinoma cells showed that FIS1 is dispensable for mitochondrial fission." (PMID 35565283, 2022).
heart failure (4 papers, 2015 to 2023). Inability of the heart to pump blood at an adequate rate to meet tissue metabolic requirements. "QSG could also act on the expression of mitochondrial fusion/split protein, upregulate the expression of MFN1/2 and OPA1, inhibit the expression of DRP1 and FIS1, and reduce mitochondrial disorders and oxidative stress damage caused by heart failure." (PMID 35003305, 2021). "Another study demonstrated that Mfn2 and OPA1 levels are reduced, while DRP1 and FIS1 levels are elevated in heart failure in dogs and humans." (PMID 37371979, 2023). "Together, inhibition of Drp1, specifically targeting Drp1/Fis1 interaction, appears to have therapeutic potential in preventing MI-induced cardiac injury and subsequent heart failure development." (PMID 25652199, 2015).
myocardial ischemia (4 papers, 2018 to 2024). A disorder of cardiac function caused by insufficient blood flow to the muscle tissue of the heart. "In myocardial ischemia–reperfusion injury, Fis1 phosphorylation may cause greater damage to mitochondrial quality than Drp1 phosphorylation." (PMID 37833768, 2023). "Consistent with these previous findings, our study demonstrated that inhibition of mitochondrial fission through the repression of the DNA-PKcs/Fis1 pathway can reduce cardiac fibrosis following myocardial ischemia-reperfusion injury." (PMID 38169612, 2024). "Moreover, in rats on myocardial ischemia–reperfusion injury conditions, miR-484 reduces Fis1 protein expression levels, a protein that inhibits mitochondria fission." (PMID 39519313, 2024). "In myocardial ischemia, the ubiquitin ligase SIAH2 can increase the Fis1-Drp1 interactions by inhibiting the PKA pathway, resulting in excessive mitochondrial fission and cardiomyocyte apoptosis." (PMID 37833768, 2023).
Parkinson disease (4 papers, 2018 to 2023). A progressive degenerative disorder of the central nervous system characterized by loss of dopamine producing neurons in the substantia nigra and the presence of Lewy bodies in the substantia nigra and locus coeruleus. "We next examined whether the oligomerization domain mutant Mid51(R169W) potentially linked to Parkinson’s disease was able to disrupt Fis1 oligomerization." (PMID 36044022, 2022). "Moreover, inhibiting Fis1 oligomerization by either mutant Fis1 or a Mid51 oligomerization mutant potentially associated with Parkinson’s disease prevents lysosomal untethering events, resulting in misregulated lysosomal network dynamics." (PMID 36044022, 2022). "For Parkinson’s disease, it was shown that these proteins Mfn2, Opa1, Drp1, and Fis1, which are involved in the control of mitochondrial fusion and fission and are downregulated in a rotenone-induced Parkinson’s disease model remained at a normal level by resveratrol administration." (PMID 37232719, 2023).
adrenocortical cancer (3 papers, 2017 to 2022). "In adrenocortical cancer cells, the microRNA miR-484 suppresses Fis1 translation and inhibits apoptosis, while miR-483-5p targets Fis1, inhibits mitochondrial fission and cisplatin sensitivity in tongue squamous cell carcinoma." (PMID 28589083, 2017). "Interestingly, Mir484 has been implicated in suppressing translation of mitochondrial fission protein FIS1 and inhibited FIS1-mediated fission and apoptosis in cardiomyocytes and adrenocortical cancer cells." (PMID 29324753, 2018).
atherosclerosis (3 papers, 2021 to 2026). A disease characterized by the build-up of fatty material and calcium deposition in the arterial wall resulting in partial or complete occlusion of the arterial lumen. "In situ images and Oil Red O staining of mouse aortas showed that Fis1 silencing in ECs accelerated and aggravated atherosclerosis lesions compared with control shRNA mice." (PMID 40135829, 2025). "Furthermore, to investigate the involvement of MAMs in atherosclerosis pathogenesis, we examined the expression of three core MAMs-related molecules—Mitofusin 1 (MFN1), Mitofusin 2 (MFN2), and Mitochondrial Fission 1 (Fis1)—in the same PBMC samples." (PMID 41614904, 2026).